AFP (alpha fetoprotein)
Diseases named in the same sentence as AFP in open-access papers (continued):
Sharing a sentence is not in itself a finding about the gene and the disease.
Hepatitis (continued). "The AUC of the AFP/AFU combination was better than any other single biomarker (only AFP or AFU) of all-stage and early-stage hepatitis-related HCC in the test and validation groups." (PMID 33628599, 2021). "But as we know, other tumour markers such as AFP, CEA and CA19‐9 can also slightly elevate in inflammatory diseases such as hepatitis and pancreatitis, but their properties as independent tumour markers are not affected." (PMID 32886424, 2020). "In a cohort of patients with hepatitis B related HCC, AFP at 200 ng/ml and 400 ng/ml showed a sensitivity of 79.8% and 91.5% respectively." (PMID 29207969, 2017). "Among 8 potential markers of HCC, only AFP and CTNNB are more than twofold more abundant in HCC compared to hepatitis." (PMID 19578489, 2008). "As noted, serum alpha‐fetoprotein and hepatitis serology were not obtained during the initial stroke workup." (PMID 41487984, 2026). "In this study, given that the patient was relatively young, had no history of hepatitis, and tested negative for AFP, we initially assessed a low likelihood of HCC during differential diagnosis." (PMID 41211439, 2025). "Moreover, in congenital tyrosinemia, cirrhosis, hepatitis (alcohol-induced), hepatitis (viral-induced), ataxia-telangiectasia syndrome or in several malignancies such as testicular cancer, liver cancer, gastric cancer and nasopharyngeal cancer elevated AFP levels may also be present." (PMID 36979610, 2023). "The most popular blood biomarker for HCC, alpha-fetoprotein (AFP), demonstrates subpar performance as a serological test in HCC surveillance due to its low sensitivity being only 10%–20% in early-stage HCC and its labile levels during hepatitis flares." (PMID 36873737, 2023). "The remaining 7 were excluded for the following reasons: 2 for lack of clear diagnosis, 1 for having a liver abscess, 1 for drug-induced hepatitis, and 3 for lack of AFP or G-test results." (PMID 36241994, 2022). "The combination of AFU with AFP raises sensitivity and specificity, especially in hepatitis-negative patients, but is worse than AFP alone in patients with HCC due to HBV." (PMID 36518320, 2022). "It is not enough to rely on ALT alone as an indicator to assess the necessity of HBV therapy, as hepatitis attacks may be accompanied by changes in several clinical indicators, such as HBsAg, HBV DNA, alpha fetoprotein (AFP), etc." (PMID 36483546, 2022). "On multivariable analysis, decreased survival was associated with Child–Pugh B disease, BCLC stage D, AJCC stage IV, bilobar tumors, nonviral hepatitis, systemic therapy, and AFP (p < 0.05)." (PMID 34318618, 2021). "Thus, AUC values of 0.853 and 0.903 were obtained for circSMARCA5 and circSMARCA5 + AFP, respectively, in the discrimination of HCC vs. Hepatitis." (PMID 34944400, 2021). "Moreover, the combination maintained diagnostic specificity and improved the sensitivity for the detection of NBNC-HCC and hepatitis-related HCC populations, when compared with AFP alone." (PMID 33628599, 2021). "In the HCC-vs-non-HCC radiomics model, gender, hepatitis, AFP, CA19-9, CEA, stage, and radiomics score were independent factors related to HCC (P < 0.05)." (PMID 33072550, 2020). "There was no abnormality in hepatitis test including hepatitis B. Serum levels of alpha-fetoprotein (AFP) were increased to 83,164.6 ng/mL (normal range, <8 ng/mL)." (PMID 32384467, 2020). "Although hepatitis B can also lead to elevated AFP, formal antiviral therapy and resulting virus DNA negative status will result in a minimal influence by hepatitis on AFP levels." (PMID 29687004, 2018). "The finding that viral load independently predicted AFP elevation may suggest direct interaction between HBV replication and AFP expression in HCC cells, in addition to hepatitis activity induced by HBV." (PMID 27997559, 2016).
Hepatitis (continued). "The recommended screening strategy for patients over 35 years old, with hepatitis B virus (HBV) and (or) hepatitis C virus (HCV) infections, includes the determination of serum alpha-fetoprotein (AFP) levels and an abdominal ultrasound every 6 months to detect HCC at an early stage." (PMID 25165471, 2014). "Early detection of HCC has been increased in patients with chronic viral and nonviral hepatitis due to screening programs with the periodical application of alpha-fetoprotein test and US every six months." (PMID 23365779, 2013). "His α-fetoprotein (AFP) level was within the normal range; our patient was not alcoholic, and he tested negative for hepatitis B and C." (PMID 22950705, 2012). "She presented with hepatomegaly and sporadic fever, and had negative hepatitis serology, normal alkaline phosphatase, and a rising serum alpha-fetoprotein level." (PMID 19918566, 2009). "Serum alpha‐fetoprotein and hepatitis serology were not obtained during the initial stroke workup." (PMID 41487984, 2026). "The absence of hepatitis of infectious etiology, high serum AFP levels, and the presence of a pancreatic mass on imaging may indicate the presence of pancreatic HAC." (PMID 40900781, 2025). "In other words, the increase in AFP does not reflect the tumor but may have been re-elevated by chemotherapy-induced hepatitis." (PMID 38071671, 2024). "In addition, we assessed the number of cases with serum AFP levels higher than 20 ng/μL and DMMs above the 95% percentile of hepatitis in non-cirrhotic HCC." (PMID 37835478, 2023). "Univariate analysis showed that ECOG score, AFP, number of tumors, distant metastasis, and history of hepatitis were not related to the median OS and TTP, but portal vein tumor thrombus, tumor size, Child-Pugh grade, and treatment modality were all related to the prognosis of the patients." (PMID 34970563, 2021). "Unfortunately, the level of AFP may be elevated in patients with nonmalignant chronic liver diseases, including approximately 40% of patients with hepatitis and 30% of patients with cirrhosis." (PMID 33628599, 2021). "Alpha‐fetoprotein (AFP), which is the most widely used blood biomarker in HCC, also shows suboptimal performance as a serological test in HCC surveillance because of fluctuations in the AFP levels during hepatitis flares and 10–20% positivity in early‐stage HCC." (PMID 32525601, 2020). "Additionally, the expression of PD-L1 was correlated with AFP, hepatitis history, and CD8+ TILs but not with other clinicopathological features." (PMID 30718977, 2019). "We observed that AFP levels were more predictive of HCC during ETV therapy at 12 months than at baseline; this is because the elevated AFP levels in patients commencing antiviral therapy were related to the hepatitis activity and were minimized through NA therapy." (PMID 29190928, 2017). "The difference between the two reference values may be due to the background of each study population; this study was planned to collect the annual laboratory data and may have failed to cover periods with hepatitis accompanied by elevated levels of AFP." (PMID 27748053, 2016). "Thus, regardless of hepatitis and abnormal AFP, MRI is recommended to search for evidence of hepatic pseudolesion." (PMID 24059753, 2013). "Clinical parameters such as sex, age, history of steroids, hepatitis or level of alpha-fetoprotein may give indications, but not proof, in the differential diagnosis." (PMID 18577240, 2008). "Therefore, the elevated AFP was likely due to hepatitis flares but not HCC." (PMID 36233438, 2022). "However, because the elevation of AFP levels by hepatitis or regeneration is usually not so high, only 200 ng/ml, AFP levels over 1,000 ng/ml might specifically indicate tumor malignancy." (PMID 22697061, 2012).
Hepatitis (continued). "The differences in gender, age, AFP, ALB, TB, ALBI grade, maximum tumor size, tumor number, hepatitis, ascites, Child–Pugh grade, and BCLC stage were not statistically significant (P>0.05), indicating a balanced baseline and comparability between the two groups." (PMID 38380330, 2024). "Hepatitis activity may decrease over the course of CHB, either with or without NA therapy, and false positivity of AFP may decrease accordingly." (PMID 29290966, 2017). "Laboratory tests showed liver function tests normal (before the initial surgery however, after the surgery SGOT, SGPT, LDH were altered three times the normal range) hepatitis markers of HAV, HBV, HCV, and HIV were negative and alpha-fetoprotein (AFP) was 35 ng/ml." (PMID 16504010, 2006).
germ cell tumor (198 papers, 1999 to 2026). A benign or malignant, gonadal or extragonadal neoplasm that originates from germ cells. "Endodermal sinus tumors (ESTs), also known as yolk sac tumors, represent 20% of germ cell tumor cases, typically arise in the ovaries, and present with a pelvic mass associated with elevated alpha‐fetoprotein (AFP) levels." (PMID 41523302, 2026). "The standard protocol for the diagnostic workup of central nervous system germ cell tumors includes MRI of the brain and spine, measurement of tumor markers (β-hCG and AFP) in both serum and cerebrospinal fluid (CSF), and histological confirmation via biopsy." (PMID 40599865, 2025). "While it is most associated with yolk sac tumors, AFP elevation can occur in rare instances with other germ cell tumor subtypes." (PMID 38380211, 2024). "First, it plays a vital role in the initial diagnosis as significantly elevated AFP levels in the blood can strongly suggest the presence of a germ cell tumor, prompting further evaluation and diagnostic procedures." (PMID 38380211, 2024). "It is necessary to combine clinical examinations and AFP level to distinguish pelvic germ cell tumors to improve the diagnostic accuracy of RMS." (PMID 33330062, 2020). "The clinical picture was dominated by a life-threatening superior vena cava syndrome with elevated alpha-fetoprotein and lactate dehydrogenase that supported the diagnostic suspicion of mediastinal germ-cell tumor." (PMID 28407756, 2017). "Similarly, one example of a mixed germ cell tumor composed of embryonal carcinoma and yolk sac tumor components was linked to elevated AFP and beta-human chorionic gonadotropin (hCG) levels." (PMID 38389620, 2024). "An elevated AFP level, as observed in our patient, is typically associated with yolk sac tumors, while CA 125 is more commonly elevated in epithelial tumors, though it may also appear in certain complex germ cell tumors." (PMID 40894989, 2025). "Therefore, the diagnostic abilities of tumor markers associated with malignant lymphomas (sIL-2R) and germ-cell tumors (hCG and AFP) may be limited given the current state of medicine." (PMID 35421961, 2022). "Consensus 2: When thymoma is suspected, blood testing for alpha‐fetoprotein and beta‐human chorionic gonadotropin concentrations is recommended to exclude germ cell tumor (97.3% agree, 2.7% disagree)." (PMID 40568789, 2025). "In germ cell tumors (GCTs), standard tumor markers include alpha-fetoprotein (AFP), beta-human chorionic gonadotropin (β-hCG), and lactate dehydrogenase (LDH), which assist in diagnosis, staging, and monitoring treatment response." (PMID 40688995, 2025). "Germ cell tumors produce specific biochemical traits involving alpha-fetoprotein (AFP) and human chorionic gonadotropin (HCG)." (PMID 40361492, 2025). "Alpha‐fetoprotein and β‐human chorionic gonadotropin determination should be performed to exclude germ cell tumor." (PMID 40568789, 2025). "Alpha-fetoprotein (AFP) is especially specific for malignant germ cell tumors such as yolk sac tumors." (PMID 41000187, 2025). "This retrospective cohort study considered AFP concentration in the context of germ-cell tumour diagnosis and characterisation at baseline (BL), disease status during chemotherapy, and long-term surveillance." (PMID 39934683, 2025). "Germ cell tumors with liver metastasis: In yolk sac tumors and embryonal carcinomas, plasma AFP is increased, and IHC staining is positive for CD30, ER, and PR." (PMID 39931054, 2025). "AFP and β-hCG remain the most relevant markers in germ cell tumors, whereas LDH was underutilized in our cohort despite its diagnostic utility." (PMID 41170462, 2025). "An increase in AFP levels indicates the presence of malignant germ cell tumors and is useful for monitoring disease progression." (PMID 40430002, 2025). "In young males, elevated levels of alpha-fetoprotein or human chorionic gonadotropin strongly suggest malignant germ cell tumors." (PMID 39944162, 2025).
germ cell tumor (continued). "Although YST is mostly present at early age of women, but an ovarian mass with elevated serum AFP level in postmenopausal women should suspect the diagnosis of germ cell tumors." (PMID 38966065, 2024). "In terms of its utility in germ cell tumors, AFP is generally elevated in embryonal cell carcinoma as well as yolk sac tumors but is not elevated in pure choriocarcinoma or pure seminoma." (PMID 39685906, 2024). "The level of AFP correlates closely with the tumor pathology; pure yolk sac tumors show significantly higher AFP levels than mixed germ cell tumors, aiding in preoperative tumor classification and postoperative efficacy and recurrence assessment." (PMID 38966065, 2024). "Management of testicular germ cell tumor has long been guided by serum tumor markers including AFP, β-hCG, and LDH." (PMID 39685906, 2024). "Tumor serum markers, including alpha-fetoprotein, beta-human chorionic gonadotropin, and lactate-dehydrogenase, were evaluated in 60 cases (21%) to exclude a germ cell tumor of the testis." (PMID 39682143, 2024). "A diagnosis of malignant germ cell tumor was made based on radiographic appearance and high alpha-fetoprotein (AFP) levels." (PMID 36805676, 2023). "Germ cell tumors are typically associated with serum tumor markers, such as human chorionic gonadotropin(HCG) and alpha-fetoprotein (AFP)." (PMID 37623476, 2023). "A combination of antibodies, including Sal-like transcription factor 4 (SALL4), octamer-binding transcription factor 3/4 (OCT3/4) and α-fetoprotein (AFP), have been used to diagnose germ cell tumors." (PMID 38090508, 2023). "Yolk sac tumors, along with mixed germ cell tumors with yolk sac components, produce high levels of AFP, which can be of great assistance for the initial diagnosis and postoperative follow-up of patients." (PMID 37508611, 2023). "Alpha-fetoprotein (AFP) has been shown to be expressed by germ cell tumors, specifically endodermal sinus tumors." (PMID 36556136, 2022). "Some germ-cell tumors secrete tumor markers (Alpha-fetoprotein (AFP) and beta-human chorionic gonadotropin (bhCG)) and can be diagnosed by identification of those markers in CSF and blood." (PMID 36670613, 2022). "The presence of alpha-fetoprotein-producing cells is an important tool in the differential diagnosis of germ cell tumors and challenging in this case of SLCT because of its rarity in this context." (PMID 35450124, 2022). "We report here a case of a 15-year-old female complaining about abdominal pain, constipation, and spaniomenorrhea with high level of serum AFP leading to a clinical suspicion of malignant germ cell tumor." (PMID 35450124, 2022). "AFP is secreted by 40–60% of patients with embryonal cell carcinoma and yolk sac tumor, while HCG is elevated in 10–20% of patients with choriocarcinoma." (PMID 34518930, 2022). "The data reported here show that the automated immunochemical method is fit for quantification of hCG and AFP in cerebrospinal fluid (CSF), allowing selective and specific diagnosis of secreting germ cell tumors." (PMID 34829327, 2021). "This was clearly demonstrated in the GETUG 13 phase III trial, which reports personalized chemotherapy based on the changes in AFP and hCG levels in poor-prognosis germ-cell tumors." (PMID 34829327, 2021). "Tumor markers such as human gonadotropin (hCG) and alpha‐fetoprotein (AFP) are mandatory to exclude germ cell tumors in younger patients with a pelvic mass or suspicious enlargement of an ovary." (PMID 34669199, 2021). "Immunohistochemical staining showed that alpha fetoprotein (AFP) was positive and the Ki-67 proliferation index was high (60%), suggesting a germ cell tumor." (PMID 34804928, 2021). "Germ-cell tumors also have a different set of biomarkers such as alpha-fetoprotein (AFP), serum human chorionic gonadotropin (HCG), and lactate dehydrogenase (LDH)." (PMID 34680193, 2021).